KHDRBS1 (KH RNA binding domain containing, signal transduction associated 1)
Description:
Recruited and tyrosine phosphorylated by several receptor systems, for example the T-cell, leptin and insulin receptors. Once phosphorylated, functions as an adapter protein in signal transduction cascades by binding to SH2 and SH3 domain-containing proteins. Role in G2-M progression in the cell cycle. Represses CBP-dependent transcriptional activation apparently by competing with other nuclear factors for binding to CBP. Also acts as a putative regulator of mRNA stability and/or translation rates and mediates mRNA nuclear export. Positively regulates the association of constitutive transport element (CTE)-containing mRNA with large polyribosomes and translation initiation. According to some authors, is not involved in the nucleocytoplasmic export of unspliced (CTE)-containing RNA species according to. RNA-binding protein that plays a role in the regulation of alternative splicing and influences mRNA splice site selection and exon inclusion. Binds to RNA containing 5'-[AU]UAA-3' as a bipartite motif spaced by more than 15 nucleotides. Binds poly(A). Can regulate CD44 alternative splicing in a Ras pathway-dependent manner. In cooperation with HNRNPA1 modulates alternative splicing of BCL2L1 by promoting splicing toward isoform Bcl-X(S), and of SMN1. Can regulate alternative splicing of NRXN1 and NRXN3 in the laminin G-like domain 6 containing the evolutionary conserved neurexin alternative spliced segment 4 (AS4) involved in neurexin selective targeting to postsynaptic partners. In a neuronal activity-dependent manner cooperates synergistically with KHDRBS2/SLIM-1 in regulation of NRXN1 exon skipping at AS4. The cooperation with KHDRBS2/SLIM-1 is antagonistic for regulation of NXRN3 alternative splicing at AS4 (By similarity). Isoform 3, which is expressed in growth-arrested cells only, inhibits S phase.
Synonyms: Sam68; p62; FLJ34027; p68
Tractability: Small molecule: it belongs to a druggable protein family. PROTAC: UniProt records ubiquitination sites on it; ubiquitination databases record sites on it; its protein half-life has been measured.
Gene: Protein-coding gene on chromosome 1 (32,013,687 to 32,060,850, forward strand). Ensembl gene ENSG00000121774.
Subcellular location: Nucleus; Cytoplasm; Membrane
Subcellular location (Human Protein Atlas): Nucleoplasm
Pathways (Reactome):
Signal Transduction: PTK6 Regulates Proteins Involved in RNA Processing
Gene Ontology:
Molecular function: identical protein binding; molecular function inhibitor activity; poly(A) binding; poly(U) RNA binding; protein binding; protein domain specific binding; protein tyrosine kinase binding; RNA binding; SH2 domain binding; SH3 domain binding; signaling adaptor activity; DNA binding; nucleic acid binding; protein-containing complex binding
Biological process: positive regulation of RNA export from nucleus; positive regulation of translational initiation; regulation of alternative mRNA splicing, via spliceosome; regulation of apoptotic process; regulation of cell cycle; regulation of protein stability; regulation of RNA splicing; T cell receptor signaling pathway; G1/S transition of mitotic cell cycle; G2/M transition of mitotic cell cycle; mRNA processing; negative regulation of DNA-templated transcription; regulation of RNA export from nucleus; cell surface receptor signaling pathway; regulation of mRNA splicing, via spliceosome; spermatogenesis
Cellular component: cytoplasm; membrane; nucleoplasm; nucleus; protein-containing complex; cytosol; Grb2-Sos complex
Genetic constraint (gnomAD): Loss-of-function variants: 5 observed, 26.69 expected, observed/expected ratio (o/e) 0.19, 90% interval 0.097 to 0.39. The synonymous counts are far from expectation, so gnomAD's model fits this gene poorly and the ratio says little. Missense variants: 366 observed, 397.54 expected, observed/expected ratio (o/e) 0.92, 90% interval 0.84 to 1. Synonymous variants: 191 observed, 153.32 expected, observed/expected ratio (o/e) 1.25, 90% interval 1.11 to 1.4.
Homologues: Orthologues: chimpanzee KHDRBS1 (100% identical), macaque KHDRBS1 (100% identical), dog KHDRBS1 (99% identical), pig KHDRBS1 (99% identical), rabbit KHDRBS1 (99% identical), guinea pig KHDRBS1 (99% identical), mouse Khdrbs1 (94% identical), rat Khdrbs1 (94% identical), tropical clawed frog khdrbs1 (63% identical), zebrafish khdrbs1b (53% identical), zebrafish khdrbs1a (51% identical), Drosophila melanogaster qkr54B (30% identical), and 7 more. Paralogues in human: KHDRBS2 (50% identical), KHDRBS3 (45% identical), QKI (27% identical), SF1 (22% identical).
Diseases named in the same sentence as KHDRBS1 in open-access papers:
KHDRBS1 is named in the same sentence as 87 diseases in open-access papers, as found by Europe PMC text mining. Sharing a sentence is not in itself a finding about the gene and the disease. The quoted sentences say what the papers report.
breast carcinoma (30 papers, 2008 to 2024). "KHDRBS1 upregulation and cytosolic localization are associated with poor prognosis in renal cell carcinoma and breast cancer, while in other types of cancers nuclear localization and high KHDRBS1 expression are associated with tumour progression and poor prognosis." (PMID 33213024, 2020). "Conversely, in cancer cells, KHDRBS1 acts as an oncogene, promoting breast cancer metastasis by upregulating EPHA3 gene, and regulating the expression of the androgen receptor splice variant AR-V7 to promote prostate cancer growth." (PMID 38660302, 2024). "KHDRBS1 has gained large attention by its abnormal expression in cancer, includes breast cancer and lung adenocarcinoma." (PMID 38660302, 2024). "KHDRBS1 is upregulated in breast cancer, gastric cancer and prostate cancer which promotes tumorigenesis." (PMID 39516455, 2024). "Here, we considered bone metastasis derived from breast carcinoma to investigate the expression in bone metastasis of biomarkers KHDRBS1, leptin, LEPR, and adiponectin." (PMID 33213024, 2020). "KHDRBS1 is upregulated in breast cancer cells and breast tumours; it can induce epithelial-to-mesenchymal transition (EMT) and migration in breast cancer cells." (PMID 33213024, 2020). "KHDRBS1 also promotes the progression of human breast cancer by up-regulating the activation of a surface antigen (EphA3), probably leading to the development of metastasis." (PMID 33213024, 2020). "A particularly interesting finding is the marked nuclear localization of KHDRBS1: in breast cancer, its overexpression in the cytosol correlates with poor prognosis." (PMID 33213024, 2020). "The correlation between KHDRBS1 expression and the expression of LEPR strengthens the idea that KHDRBS1 is implicated downstream of the LEPR in metastatic cells, as has been reported in breast cancer cells." (PMID 33213024, 2020). "Bone metastases from breast cancer express components of the leptin/LEPR/KHDRBS1 axis in an expression pattern that partly follows that of the primary tumour but also exhibits peculiarities." (PMID 33213024, 2020). "KHDRBS1 is also involved in the signalling pathway of leptin receptor (LEPR) in breast cancer cells as a transducer that mediates the effects of the hormone on cell proliferation and growth." (PMID 33213024, 2020). "SAM68 (also known as KH-domain-containing, RNA-binding, signal-transduction-associated 1 (KHDRBS1)) plays vital roles in human cancers including lung adenocarcinoma, hepatic gluconeogenesis, and breast cancer." (PMID 38892138, 2024). "Here, we investigated the expression and the intracellular distribution of KH RNA binding domain containing, signal transduction associated 1 (KHDRBS1), leptin, leptin receptor (LEPR), and adiponectin in bone metastasis from breast carcinoma and looked for correlations between the data." (PMID 33213024, 2020). "The functions of KHDRBS1 have been recently correlated with tumour progression in breast cancer." (PMID 33213024, 2020). "The leptin/LEPR/KHDRBS1 axis, whose components have been studied in breast cancer, may also be expressed in metastatic tissue and contribute to colonization." (PMID 33213024, 2020). "With the present study, we investigated the expression and the intracellular distribution of KHDRBS1, leptin, and LEPR in bone metastasis from breast carcinoma and looked for eventual correlations between them." (PMID 33213024, 2020). "Moreover, the positive correlation between KHDRBS1 expression and the expression of matrix-metalloproteinase-9 (MMMP-9) in breast cancer tissue supports the role of KHDRBS1 in the promotion of breast cancer metastasis." (PMID 33213024, 2020). "The pattern of tissue distribution of KHDRBS1, leptin, and LEPR in bone metastases from breast cancer is unknown." (PMID 33213024, 2020).
prostate carcinoma (25 papers, 2009 to 2025). A carcinoma that arises from epithelial cells of the prostate gland. "Previous studies have implicated KHDRBS1 in the oncogenesis of certain human tumors such as colorectal and prostate cancers, underscoring its potential as a therapeutic target." (PMID 38660302, 2024). "The eight proteins highlighted in this study (KLK3, SORD, SPON2, IMPDH2, ACTN4, ATP1B1, HSPB1, and KHDRBS1) represent a signature associated with AR modulation during the transition from androgen-dependent to castration-resistant prostate cancers." (PMID 29966326, 2018). "Researches have indicated that KHDRBS1 is upregulated in colon cancer, prostate cancer, kidney cancer and colorectal cancer." (PMID 39516455, 2024).
colon carcinoma (12 papers, 2016 to 2025). "KHDRBS1 null mice produced delays in colon tumor growth, metastasis, cell migration, and extremely sensitiveness to agents that cause DNA damage." (PMID 31440515, 2019). "Accordingly, KHDRBS1 downregulation promotes self-destruction of colon cancer cells under exposure to DNA-damaging agents." (PMID 31440515, 2019). "In contrast, colon tumor development, as reflected by both tumor size and tumor load, in Apcmin716/+; Khdrbs1-/- mice was dramatically reduced; albeit genetic deletion of Sam68 in Apcmin716/+ mice did not significantly affect tumor number." (PMID 27458801, 2016).
colorectal cancer (8 papers, 2018 to 2024). A primary or metastatic malignant neoplasm that affects the colon or rectum. "One study showed that linc00152 is capable of complex formation with two RNA binding proteins, NCL (nucleolin) and Sam68 (KHDRBS1, the src-associated substrate in mitosis of 68kDa), which are responsible for the development of colorectal cancer via NF-κB pathway activation." (PMID 31896236, 2019).
lung adenocarcinoma (7 papers, 2019 to 2024). A carcinoma that arises from the lung and is characterized by the presence of malignant glandular epithelial cells. "KHDRBS1 also regulate metabolic conversion in lung adenocarcinoma and oral squamous cell carcinoma." (PMID 39516455, 2024). "KHDRBS1 serves as a prognostic marker for kidney renal papillary cell carcinoma (KIRP), lung adenocarcinoma (LUAD), and acute myeloid leukemia (LAML)." (PMID 39717265, 2024). "Within specific cancer, including kidney renal papillary cell carcinoma (KIRP), lung adenocarcinoma (LUAD), acute myeloid leukemia (LAML), and ovarian cancer (OV), KHDRBS1 expression is heterogeneous and patient specific." (PMID 31366900, 2019).
gastric cancer (4 papers, 2019 to 2024). A primary or metastatic malignant neoplasm involving the stomach. "These SFs were markedly upregulated in ACTHomas, which is in accordance with the increased expression of KHDRBS1 found in gastric cancer, epithelial ovarian cancer or sacral chordomas, wherein its presence was associated with poor prognosis and aggressive characteristics." (PMID 31561558, 2019). "Deficiency in 3’UTR may contribute to the onset of various cancers which in turn accelerate the development of target therapy, for instance, the shortening of the KHDRBS1 mRNA 3’UTR can mediate the upregulation of KHDRBS1 and promote the progression of gastric cancer." (PMID 36601127, 2022).
lymphoma (4 papers, 2008 to 2021). A malignant (clonal) proliferation of B- lymphocytes or T- lymphocytes which involves the lymph nodes, bone marrow and/or extranodal sites. "Lymphomas expressed the KHDRBS1-LCK fusion protein, which was highly phosphorylated." (PMID 34140493, 2021). "Here we validated PLAIDOH’s functional predictions for RP11-960 L18.1, confirming that it is not a cis-regulatory lncRNA for PLCG2, but rather likely acts in the cytoplasm by interacting with one or more RBPs (NF90, KHDRBS1, PUM2) to promote the growth of lymphoma cells." (PMID 30767760, 2019).
viral infection (4 papers, 2013 to 2024). "Significant associations were observed between KHDRBS1 gene expression and patients’ tumor T stage and viral infection status." (PMID 38660302, 2024). "Finally, comparative box plots across various clinical features revealed significant differences in KHDRBS1 gene expression levels under certain clinical conditions such as viral infection status and tumor T stage." (PMID 38660302, 2024).
fragile X-associated tremor/ataxia syndrome (3 papers, 2013 to 2021). Fragile X-associated tremor/ataxia syndrome (FXTAS) is a rare neurodegenerative disorder characterized by adult-onset progressive intention tremor and gait ataxia. "Another splicing factor involved in neuronal functions is Sam68, encoded by the Khdrbs1 gene, which is highly expressed in brain and testis, and it was shown to be involved in the pathogenesis of fragile X tremor/ataxia syndrome and spinal muscular atrophy." (PMID 27845622, 2016).
glioblastoma (3 papers, 2021 to 2025). The most malignant astrocytic tumor (WHO grade IV). "We mainly verified the regulatory effects of KHDRBS1, SNORD51 and ZBED6 on pentose phosphate pathway and malignant biological behavior in glioblastoma cells, such as proliferation, migration and invasion." (PMID 39516455, 2024). "KHDRBS1 is upregulated in GBM cells and promotes the growth of glioblastoma." (PMID 39516455, 2024).
glioma (3 papers, 2009 to 2024). A benign or malignant brain and spinal cord tumor that arises from glial cells (astrocytes, oligodendrocytes, ependymal cells). "Furthermore, the Cancer Genome Atlas Program (TCGA) database showed that KHDRBS1 was significantly associated with poor prognosis of glioma." (PMID 39516455, 2024). "ALDH1A3 promotes self-renewal and clonogenic potential of glioma stem cells, suggesting that its reduced expression may account for the phenotype of Khdrbs1-/- NPCs." (PMID 27845622, 2016).
melanoma (3 papers, 2017 to 2026). A malignant, usually aggressive tumor composed of atypical, neoplastic melanocytes. "First, CRISPR activation screens in melanoma cells identify functionally diverse regulators of TCR-specific cytotoxicity, including SAFB, KHDRBS1, MYC, CD44, WNT3A, WNT1 and others." (PMID 41946842, 2026).
adenoma (2 papers, 2016). A neoplasm arising from the epithelium. "Apcmin716/+; Khdrbs1+/- mice, compared to wild-type controls, spontaneously developed adenomas in the cecum and distal colon at 3 months of age, as conveyed by whole mount methylene blue staining and showed substantial increases in the size and load of tumors." (PMID 27458801, 2016).
multiple myeloma (2 papers, 2022 to 2024). "In this study, 17-AAG, an HSP90 inhibitor candidate in human clinical trials (multiple myeloma; phase 3), potentially exerted an inhibitory activity on EZH2, PAX5 and KHDRBS1 genes associated with the risk of developing metastatic phenotypes by modulating gene expression." (PMID 38254687, 2024).
osteosarcoma (2 papers, 2023 to 2024). A usually aggressive malignant bone-forming mesenchymal neoplasm, predominantly affecting adolescents and young adults. "Interestingly, three proteins, KHDRBS1, FUBP1, and HNRNPA2B1, are involved in either RNA processing or RNA modification, highlighting the potential role of RNA regulation in osteosarcoma pathogenesis." (PMID 37681913, 2023).
ACTHomas (1 paper, 2019). "In ACTHomas, our results demonstrated that the altered expression of only two SFs, MAGOH and KHDRBS1, was sufficient to fully discriminate ACTHomas from NPs." (PMID 31561558, 2019). "Indeed, these two SFs (MAGOH and KHDRBS1) were markedly overexpressed in ACTHomas, and ROC curves of these SFs corroborated their capacity to discriminate between ACTHomas and NPs with an AUC of 1 and 0.97, respectively (p < 0.0001)." (PMID 31561558, 2019). "Conversely, PLS-DA analysis showed a clear separation between ACTHomas and NPs, and the VIP score of PLS-DA analysis revealed that the pattern of two SFs with the highest score (MAGOH and KHDRBS1) was able to discriminate between ACTHomas and NPs." (PMID 31561558, 2019).
adult T-cell leukemia/lymphoma (1 paper, 2021). A peripheral (mature) T-cell neoplasm linked to the human T-cell leukemia virus type 1 (HTLV-1), adult T-cell leukemia/lymphoma is endemic in several regions of the world, in particular Japan, the Caribbean, and parts of Central Africa. "To validate the importance of these fusion genes, we tested the presence of the FYN-TRAF3IP2 and the KHDRBS1-LCK fusion genes with RT-PCR in an independent validation cohort of 37 PTCL cases (30 PTCL-NOS, 6 PTCL-TFH, 1 Adult T-cell leukemia/lymphoma (ATLL))." (PMID 34140493, 2021).
atherosclerosis (1 paper, 2021). A disease characterized by the build-up of fatty material and calcium deposition in the arterial wall resulting in partial or complete occlusion of the arterial lumen. "We analyzed these microRNAs and selected those that have the possibility to regulate atherosclerosis and evolutionarily conserved, including, miR-30d-3p and miR-140-3p, which had conserved binding sites with mmu_circRNA_37699 (circRNA KHDRBS1) and mmu_circRNA_36781 (circRNA ABCA1)." (PMID 34307490, 2021). "Other targets and signaling pathways that may be regulated by miR-30d-3p and miR-140-3p were also predicted and analyzed to provide a basis for further studies on the regulation of circRNA KHDRBS1 and circRNA ABCA1 in vascular endothelial injury and atherosclerosis." (PMID 34307490, 2021).
dementia (1 paper, 2024). Loss of intellectual abilities interfering with an individual's social and occupational functions.
hepatocellular carcinoma (1 paper, 2024). A malignant tumor that arises from hepatocytes. "Thus, our findings strongly suggest a role for KHDRBS1 in promoting malignant characteristics of hepatocellular carcinoma." (PMID 38660302, 2024). "Additionally, our study highlights the close correlation between KHDRBS1 expression levels and immune evasion, as well as adverse prognosis in hepatocellular carcinoma." (PMID 38660302, 2024). "However, the comprehensive expression pattern of KHDRBS1 in hepatocellular carcinoma (HCC) warrants further exploration." (PMID 38660302, 2024). "In order to enhance the credibility of KHDRBS1 as a potential oncogenic gene in hepatocellular carcinoma (HCC), validation analyses were performed on two separate supplementary cohorts to confirm the correlation between KHDRBS1 expression levels and tumor-associated characteristics." (PMID 38660302, 2024).